TRAV1-1 (T cell receptor alpha variable 1-1)
Description:
V region of the variable domain of T cell receptor (TR) alpha chain that participates in the antigen recognition. Alpha-beta T cell receptors are antigen specific receptors which are essential to the immune response and are present on the cell surface of T lymphocytes. Recognize peptide-major histocompatibility (MH) (pMH) complexes that are displayed by antigen presenting cells (APC), a prerequisite for efficient T cell adaptive immunity against pathogens. Binding of alpha-beta TR to pMH complex initiates TR-CD3 clustering on the cell surface and intracellular activation of LCK that phosphorylates the ITAM motifs of CD3G, CD3D, CD3E and CD247 enabling the recruitment of ZAP70. In turn ZAP70 phosphorylates LAT, which recruits numerous signaling molecules to form the LAT signalosome. The LAT signalosome propagates signal branching to three major signaling pathways, the calcium, the mitogen-activated protein kinase (MAPK) kinase and the nuclear factor NF-kappa-B (NF-kB) pathways, leading to the mobilization of transcription factors that are critical for gene expression and essential for T cell growth and differentiation. The T cell repertoire is generated in the thymus, by V-(D)-J rearrangement. This repertoire is then shaped by intrathymic selection events to generate a peripheral T cell pool of self-MH restricted, non-autoaggressive T cells. Post-thymic interaction of alpha-beta TR with the pMH complexes shapes TR structural and functional avidity.
Synonyms: TRAV11; TCRAV1S1; TCRAV7S1
Gene: T-cell receptor variable (V) gene on chromosome 14 (21,621,838 to 21,622,567, forward strand). Ensembl gene ENSG00000255569.
Subcellular location: Cell membrane
Gene Ontology:
Biological process: response to bacterium
Cellular component: plasma membrane
Homologues: Orthologues: chimpanzee TRAV1-1 (85% identical), macaque TRAV1-1 (83% identical), mouse Trav1 (63% identical). Paralogues in human: TRAV1-2 (81% identical), TRAV13-1 (31% identical), TRAV36DV7 (31% identical), TRAV20 (31% identical), TRAV7 (31% identical), TRAV5 (30% identical), TRAV10 (28% identical), TRAV17 (28% identical), TRAV13-2 (27% identical), TRAV21 (27% identical), TRAV38-1 (27% identical), TRAV39 (27% identical), and 11 more.
Diseases named in the same sentence as TRAV1-1 in open-access papers:
TRAV1-1 is named in the same sentence as 1 disease in open-access papers, as found by Europe PMC text mining. Sharing a sentence is not in itself a finding about the gene and the disease.
TRAV1-1 shares sentences with these, for which no sentence is quoted: COVID-19 (1 paper).